ST3GAL6 (ST3 beta-galactoside alpha-2,3-sialyltransferase 6)
Description:
Transfers the sialyl residue from CMP-N-acetyl-beta-neuraminate to the terminal galactose residue on sugar chains of glycoproteins and glycolipids. Its alpha-2,3-sialyltransferase activity is specific toward type II glycan chains (Galbeta1-4GlcNAc) on glycoproteins and glycolipids such as neolactosides nLc4Cer and nLc6Cer, whose sialyl-products serve as precursors for the Lewis X antigen. Critically involved in the synthesis of functional selectin ligands needed for neutrophil recruitment during inflammation and lymphocyte homing to the lymph nodes (By similarity).
Synonyms: ST3GalVI; SIAT10
Tractability: Antibody: UniProt predicts a signal peptide or a membrane-spanning region. PROTAC: its protein half-life has been measured.
Gene: Protein-coding gene on chromosome 3 (98,732,175 to 98,821,201, forward strand). Ensembl gene ENSG00000064225.
Subcellular location: Golgi apparatus membrane
Pathways (Reactome):
Metabolism: Keratan sulfate biosynthesis; Lewis blood group biosynthesis
Metabolism of proteins: Sialic acid metabolism
Signal Transduction: Pre-NOTCH Processing in Golgi
Gene Ontology:
Molecular function: N-acetyllactosaminide alpha-2,3-sialyltransferase activity; beta-galactoside (CMP) alpha-2,3-sialyltransferase activity; sialyltransferase activity
Biological process: cellular response to interleukin-6; glycolipid biosynthetic process; glycoprotein biosynthetic process; keratan sulfate proteoglycan biosynthetic process; oligosaccharide biosynthetic process
Cellular component: extracellular exosome; Golgi membrane; membrane
Genetic constraint (gnomAD): Loss-of-function variants: 17 observed, 26.48 expected, observed/expected ratio (o/e) 0.64, 90% interval 0.44 to 0.96. The upper end of that interval is the gene's LOEUF score, 0.96, which puts it in group 4 of 6, group 1 being the genes least tolerant of losing a copy. Missense variants: 264 observed, 313.79 expected, observed/expected ratio (o/e) 0.84, 90% interval 0.76 to 0.93. Synonymous variants: 100 observed, 111.87 expected, observed/expected ratio (o/e) 0.89, 90% interval 0.76 to 1.06.
Homologues: Orthologues: macaque ST3GAL6 (100% identical), chimpanzee ST3GAL6 (99% identical), dog ST3GAL6 (93% identical), guinea pig ST3GAL6 (89% identical), pig ST3GAL6 (88% identical), rat St3gal6 (75% identical), mouse St3gal6 (74% identical), rabbit ST3GAL6 (67% identical), tropical clawed frog st3gal6 (55% identical). Paralogues in human: ST3GAL4 (36% identical), ST3GAL3 (32% identical), ST3GAL5 (30% identical), ST6GALNAC2 (21% identical), ST6GALNAC1 (21% identical), ST3GAL1 (21% identical), ST6GAL2 (19% identical), ST3GAL2 (18% identical), ST6GAL1 (16% identical), ST6GALNAC3 (16% identical), ST6GALNAC4 (16% identical), ST6GALNAC6 (15% identical), and 2 more.
Diseases named in the same sentence as ST3GAL6 in open-access papers:
ST3GAL6 is named in the same sentence as 42 diseases in open-access papers, as found by Europe PMC text mining. Sharing a sentence is not in itself a finding about the gene and the disease. The quoted sentences say what the papers report.
multiple myeloma (9 papers, 2015 to 2024). "Knockdown of ST3GAL6 was observed to attenuate cell trans-endothelial migration ability, while elevation of ST3GAL6 expression was found to be associated with low overall survival in multiple myeloma patients." (PMID 39123480, 2024). "In patients with multiple myeloma, high expression of ST3Gal6, which catalyzes the 2,3-linked attachment of sialic acid residues to glycoproteins, correlates with lower overall survival." (PMID 31195728, 2019). "Knocking down ST3Gal6 decreased the levels of α2-3-linked sialic acid, impaired transendothelial migration of myeloma cell in vitro, and importantly reduced homing in vivo, indicating that the levels of selectin ligands influences myeloma trafficking into the bone marrow niche." (PMID 27148485, 2016). "The α2-3-sialyltransferases ST3Gal4 and ST3Gal6 are critical to the generation of functional E- and P-selectin ligands and overexpression of these STs have been linked to increased risk of metastatic disease in solid tumors and poor outcome in multiple myeloma." (PMID 27148485, 2016). "For example, the reduction of ST3GAL6 was frequently detected in colorectal cancer and lung adenocarcinoma; while ST3GAL6 overexpression promoted bladder cancer cell invasion and homing/survival of multiple myeloma cells." (PMID 37468844, 2023). "High expression of ST3GAL6 has been found in different cancers, including breast, multiple myeloma, and hepatocellular carcinoma, whereas normal tissues showed lower expression levels." (PMID 36476410, 2022). "The overexpression of ST3GAL6 has been reported in multiple cancers, such as breast cancer, multiple myeloma and hepatocellular carcinoma, whereas low expression level in their normal counterparts 43-45." (PMID 32929335, 2020). "Knockdown of ST3GAL6 in multiple myeloma cells diminished the cells’ ability to undergo trans-endothelial migration and reduced ability to roll on P-selectin in vitro." (PMID 31195728, 2019). "Decreasing levels of ST3GAL6 can lead to decreasing migration and invasion in 5637 and J82 UBC cells as well as decreasing adhesion and migration in multiple myeloma cells." (PMID 34943806, 2021). "In this study, we found SEs driving known oncogenes (ST3GAL6 and ADM) as w critical subtype-specific drivers (MAF and NUAK1) in myeloma pathogenesis." (PMID 33579893, 2021).
hepatocellular carcinoma (7 papers, 2019 to 2024). A malignant tumor that arises from hepatocytes. "For example, ST3GAL6 overexpression is required for multiple myeloma cell homing to bone marrow niche and subsequent tumor growth, while ST3GAL6 can induce AKT/mTOR signaling to promote hepatocellular carcinoma cell proliferation and invasion." (PMID 36092699, 2022). "ST3GAL6 expression is significantly suppressed in hepatocellular carcinoma patients, and it mediates colorectal cancer progression through the PI3K/Akt signaling." (PMID 33619235, 2021). "ST3Gal6 is also upregulated in human hepatocellular carcinoma (HCC) tissues, and correlates with cell proliferation, migration and invasion ability in HCC cell lines." (PMID 34975914, 2021). "In hepatocellular carcinoma (HCC), the microRNA miR-26a can reduce tumor growth by suppressing the Akt/mTOR pathway through targeting ST3GAL6." (PMID 31117943, 2019).
bladder cancer (5 papers, 2020 to 2026). "The key model gene ST3GAL6 was upregulated in bladder cancer tissues and was closely associated with prognosis." (PMID 42279297, 2026). "For instance, our group reported that ST3GAL6 overexpression was negatively associated with luminal subtype of bladder cancer and required for cancer cells invasion, while ST3GAL5 overexpression was correlated with CD8+ T cell exhaustion in clear cell renal cell carcinoma." (PMID 37468844, 2023). "In GC-resistant bladder cancer cells, ST3GAL6 expression was significantly increased and accompanied by enhanced sialylation activity." (PMID 42279297, 2026). "ST3GAL6 promoted bladder cancer cell proliferation and reduced sensitivity to cisplatin and gemcitabine, at least in part through the PI3K-AKT-mTOR pathway." (PMID 42279297, 2026). "Analysis of TCGA-BLCA gene expression data revealed that elevated ST3GAL6 levels were positively correlated with advanced tumor stage, higher tumor grade, and reduced overall survival in bladder cancer patients." (PMID 40252176, 2025). "On the other hand, overexpression of ST3GAL6 has been shown to promote migration and enhance metastatic potential of bladder cancer cells." (PMID 40252176, 2025). "Similar to the cancer type-dependent role of ST3GAL5, ST3GAL6 is upregulated in liver cancer and multiple myeloma, as well as the basal subtype of bladder cancer, but downregulated in colorectal cancer." (PMID 36092699, 2022). "By the unsupervised hierarchy clustering analysis on glycogenes, our previous study has identified ST3GAL6 as a poor prognostic biomarker in bladder cancer, suggesting that we can identify key drivers from glycogenes for tumor aggressiveness." (PMID 36092699, 2022). "Furthermore, ST3GAL6 overexpression enhanced bladder cancer cell migration and invasiveness, whereas ST3GAL6 knockdown suppressed these aggressive features." (PMID 40252176, 2025). "Loss of GATA3 in non-luminal bladder cancer subtypes may relieve this repression, leading to increased ST3GAL6 expression and a more invasive tumor phenotype." (PMID 40252176, 2025). "Our previous study also revealed that ST3GAL6 can be repressed by a luminal-specific transcription factor, GATA3, in bladder cancer cells." (PMID 36092699, 2022). "Ultimately, strategies involving ST3GAL5 and ST8SIA1 overexpression, or inhibition of ST3GAL6, FUT4 and FUT7, could offer new therapeutic avenues for bladder cancer." (PMID 40252176, 2025).
colorectal cancer (5 papers, 2021 to 2024). A primary or metastatic malignant neoplasm that affects the colon or rectum. "For example, in colorectal cancer, an increase in the expression of ST8SIA4, ST3GAL6, ST6GALNAC5 is associated with an increase in regulatory T cells and pro-tumoral M2 macrophages." (PMID 36009354, 2022).
breast carcinoma (4 papers, 2016 to 2024). "ST3GAL6 (β-galactose α-2, 3-sialyltransferase) modifies ligand synthesis, and its high level was associated with breast cancer metastasis." (PMID 36476410, 2022). "Higher expression of LFNG was correlated with better survival in breast cancer, while ST3GAL6 expression was correlated with poor survival." (PMID 36476410, 2022). "Accordingly, our results showed LFNG expression was lower in basal/claudin-low breast cancer compared to other subtypes and normal group (P-value < 0.0001) while ST3GAL6 has the highest expression in basal/claudin-low breast cancer (P-value < 0.0001)." (PMID 36476410, 2022). "Furthermore, high expression of LFNG (P-value < 0.001) and lower expression of ST3GAL6 (P-value = 0.012) was significantly related to better survival in breast cancer." (PMID 36476410, 2022). "In addition, the data revealed that expressional levels of ST3GAL6 (12.34-folds) and ST8SIA4 (5.71-folds) were upregulated in the highly metastatic breast cancer cell line MDA-MB-231 compared with the slightly metastatic breast cancer cell line MCF-7." (PMID 28032858, 2016). "ST3GAL6 expression was significantly higher in grade III than II of breast cancer (P-value = 0.0002); however, there was no significant change between different stages of breast cancer." (PMID 36476410, 2022).
gastric cancer (4 papers, 2014 to 2024). A primary or metastatic malignant neoplasm involving the stomach. "We evaluate the response to targeted treatment of glycoengineered gastric cancer cell models overexpressing the sialyltransferases ST3GAL4 or ST3GAL6 by subjecting 3D spheroids to the tyrosine kinase inhibitor crizotinib." (PMID 31979110, 2020). "We show here that 3D spheroids of ST3GAL4 or ST3GAL6 overexpressing MKN45 gastric cancer cells are less affected by the inhibitor." (PMID 31979110, 2020). "B4GALNT2 and ST3GAL6 have been found to be epigenetically silenced in colon and gastric cancer cells and shown to be re-expressed after 5-Aza treatment." (PMID 25294702, 2014). "In a previous work, the human gastric cancer cell line MKN45, which showed low or undetectable expression levels of the sialyltransferases ST3GAL4 and ST3GAL6, respectively, was stably transfected with the expression vector containing the respective full length cDNA encoding for ST3GAL4 and ST3GAL6." (PMID 31979110, 2020).
liver cancer (3 papers, 2020 to 2024). An epithelial or non-epithelial malignant neoplasm that arises from the liver. "ST3GAL6 is negatively regulated by miR-26a in liver cancer cells through binding to its 3′UTR region." (PMID 36092699, 2022).
melanoma (3 papers, 2021 to 2024). A malignant, usually aggressive tumor composed of atypical, neoplastic melanocytes. "Similar to our findings tissue, melanoma cell lines are enriched in the expression of genes associated with the metabolism of sialic acid, including the sialyltransferases ST3GAL4 and ST3GAL6." (PMID 38384845, 2024). "In TvHdb RVYLDIVTPK (IFT81) was identified exclusively in melanoma samples (in 17 of 31 HLA-A*03:01/A*11:01/A*31:01-positive tumor metastases or patient-derived cell lines) and RLSSSLPSR (ST3GAL6) was identified in melanoma (in 9 of 31 HLA-A*03:01/A*11:01/A*31:01-positive melanoma samples)." (PMID 39835134, 2024). "RNA-sequencing data from the TCGA melanoma database revealed that the sialyltransferases ST3GAL5, ST6GALNAC2 and ST3GAL6 are consistently expressed in the investigated melanoma samples." (PMID 34440905, 2021).
colon cancer (2 papers, 2013 to 2020). "For example, we previously showed that the synthesis of MUC1-associated sLex in HCT15 colon cancer cells was controlled by methylation of the ST3GAL6 promoter." (PMID 23451223, 2013).
meningioma (2 papers, 2021 to 2024). A generally slow growing tumor attached to the dura mater. "The expression of ST3GAL6 was reduced in both glycated meningioma cell lines, which is known to play a key role in the generation of functional Sialyl Lewis X." (PMID 34943806, 2021). "In the GEO database, mRNA expression of ST3GAL4 was significantly decreased in grade II and III meningiomas (P < 0.05), while the others (ST3GAL1, ST3GAL3, ST3GAL6, ST6GAL1, and ST6GALNAc1) were not." (PMID 38274327, 2024).
Obesity (2 papers, 2010 to 2017). Accumulation of substantial excess body fat. "Our results in the MZ twins agree with this finding and given the strong correlation of the transcript with obesity in the unrelated individuals (Pearson correlation −0.47, P = 2.48×10−5), this makes ST3GAL6 a potentially interesting new candidate." (PMID 20532202, 2010).
astrocytoma (1 paper, 2017). "Moreover, high expression of 7 of the high-malignant genes (C7ORF46, DUSP4, HS3ST3B1, ODZ1, TTL, VAV3, ZDHHC23) or low expression of 4 of the low-malignant genes (AKR1C3, ARHGEF10L, SMAD7, ST3GAL6) was associated with a lower progression free survival probability of grade III astrocytoma patients." (PMID 29152145, 2017).
autoimmune hypothyroidism (1 paper, 2024). "A common genetic etiology was proposed between hypothyroidism and OLP81 and our study supports this, indicating variation at nine loci (IFIH1, LPP, CEP43, TNRC18, C12orf42, TNFSF11, ST3GAL6, IL2RA, and IKZF3) that are strongly associated with both LP and autoimmune hypothyroidism." (PMID 38776927, 2024).
coronary heart disease (1 paper, 2022). "In contrast, UNC5D, ST3GAL6, SCG3, and IGFBP1, which are negatively affected by noisy workplace environments, are potentially protective factors against coronary heart disease (UNC5D), type 2 diabetes (UNC5D), tinnitus (ST3GAL6, SCG3), and rheumatoid arthritis (IGFBP1)." (PMID 35602164, 2022).
diabetes (1 paper, 2015). "St3gal6 is the most highly expressed α2,3 sialyltransferases in kidney IM; however, St3gal4 is the most significantly changed α2,3 sialyltransferases in diabetes, and may be responsible for the increased UT-A1 sialylation." (PMID 26483702, 2015).
lung carcinoma (1 paper, 2022). "In the LUAD specimens, ST3GAL6 was slightly reduced in lung cancer cells from a LUAD patient with stage 1 (case 1), while ST3GAL6 was barely detected in the lung cancer cells from a LUAD patient with stage 3 (case 2)." (PMID 36092699, 2022).
Miscarriage (1 paper, 2021). A pregnancy that ends at a stage in which the fetus is incapable of surviving on its own, defined as the spontaneous loss of a fetus before the 22th week of pregnancy. "Immunohistochemical staining further indicated that Lewis antigens were downregulated in miscarriage groups and key modulators including, ST3GAL6 and NEU1, might be responsible for these alterations." (PMID 34135905, 2021). "The expression of four mentioned carbohydrate Lewis antigens and their potential modulators, ST3GAL6 and NEU1, in the placenta of patients with miscarriages was significantly different from the normal pregnancy." (PMID 34135905, 2021).
prostate carcinoma (1 paper, 2025). A carcinoma that arises from epithelial cells of the prostate gland. "The tumor aggressiveness of prostate cancer cell lines has been linked to the expression of GALNT5 and ST3GAL6, mediating the synthesis of α2–3 sialic acids and especially sialyl-LewisA on MUCs in prostate cancer cell lines." (PMID 40885395, 2025).
renal carcinoma (1 paper, 2022). A carcinoma arising from the epithelium of the renal parenchyma or the renal pelvis. "Previous studies revealed that ST3GAL1 may account for sialylation of EGFR in renal cancer cells, while ST3GAL6 may promote sialylation of EGFR in HeLa cells." (PMID 36092699, 2022).
serous ovarian cancer (1 paper, 2014). "Similarly ARID3B overexpressing cells exhibited increased expression of genes (ST3GAL6, ADAM19, and HTATIP2) reported to be part of the serous ovarian cancer ascites CSC signature." (PMID 25327563, 2014).
thymoma (1 paper, 2023). A neoplasm arising from the epithelial cells of the thymus. "Furthermore, the clinical data showed that high expression level of B3GNT5 in thymoma was associated with worse disease-free survival (p < 0.05, HR = 0.3339, 95%CI 0.1204-0.9263), while ST3GAL6 expression didn't influence DFS (p > 0.05, HR = 1.995, 95%CI 0.7339-5.424)." (PMID 37781041, 2023). "Expression of B3GNT5 and ST3GAL6 was upregulated in thymoma tissues than adjacent normal thymic tissues (p < 0.05)." (PMID 37781041, 2023).
Tinnitus (1 paper, 2022). Tinnitus is an auditory perception that can be described as the experience of sound, in the ear or in the head, in the absence of external acoustic stimulation. "The present study showed that noisy workplaces decreased plasma concentrations of ST3GAL6 and SCG3, proteins thought to protect against tinnitus." (PMID 35602164, 2022).